SPARC (secreted protein acidic and cysteine rich)
Diseases named in the same sentence as SPARC in open-access papers (continued):
Sharing a sentence is not in itself a finding about the gene and the disease.
bladder cancer (15 papers, 2004 to 2024). "The SPARC level in human bladder cancer cell lines is negatively associated with the proliferation rate." (PMID 37577749, 2023). "A study using an oncogene-induced model of bladder cancer in SPARC WT and SPARC-/- mice, demonstrated that the loss of SPARC promotes the inflammatory phenotype of TAMs (as well as CAFs) through the activation of the transcription factors NF-κB and AP-1." (PMID 33466303, 2021). "Moreover, we found that this adhesion and targeting were associated with the abundance of SPARC expression in bladder cancer cells." (PMID 37062822, 2023). "Herein, we review the current knowledge of the role and association of SPARC in bladder cancer." (PMID 27564266, 2016). "A significant correlation with MMP-2 gene expression implies that the regulation of MMP-2 may be a possible mechanism underlying the effect of SPARC on the progression of oesophageal and bladder cancer." (PMID 15558074, 2004). "Murine carcinoma-associated fibroblasts (CAFs) extracted from SPARC−/− bladder carcinomas also exhibit enhanced inflammatory phenotypes via NF-κB and AP-1 signaling, thereby promoting tumor growth and metastasis, indicating a tumor-suppressive role of SPARC in bladder CAFs." (PMID 31067787, 2019). "After culturing the respective bladder cancer cells for 36 h, the culture supernatant was taken, and the expression levels of SPARC was measured in the supernatant according to the instructions of the Boster SPARC ELISA kit." (PMID 37062822, 2023). "In this study, we found that E. coli surface-modified by BSA had stronger adhesion and targeting effects on bladder cancer cells with high expression of SPARC." (PMID 37062822, 2023). "SPARC can be used as a prospective therapeutic index and prognostic biomarker for cancers including rectal cancer, bladder cancer, and head and neck cancer." (PMID 37577749, 2023). "The level of the SPARC gene has a significant relationship with the histological type, pathological status, and prognosis of bladder cancer." (PMID 37577749, 2023). "In the DepMap database, we searched bladder cancer cell lines with different SPARC expression levels." (PMID 37062822, 2023). "In contrast, some other studies found that SPARC expression was reduced in bladder cancer and acute leukemia." (PMID 34899080, 2021). "Chemical agent-induced bladder carcinomas have been shown to grow and progress more significantly in SPARC−/− mice than in control SPARC+/+ mice." (PMID 31067787, 2019). "The role of tumor-SPARC in lung colonization was further investigated in a human experimental metastasis model, injecting human bladder cancer cells genetically modified for SPARC expression into nude mice." (PMID 27564266, 2016). "The contribution of cancer cell- vs. stromal cell- SPARC in bladder cancer metastasis was dissected using multiple independent approaches." (PMID 27564266, 2016). "SPARC expression in human bladder cancer cell lines inversely correlated with their proliferation rate, restrained cell cycle progression through slowing G1/S cell cycle proteins, cyclins A1, D1 and E2 with increase of their inhibitors p21CIP/WAF1 and p27KIP1." (PMID 27564266, 2016). "Of note, bladder cancer cells depleted of SPARC exhibited a dramatic decrease in early lung colonization implicating a counter-adhesive effect of SPARC inhibiting tumor cell adhesion to pulmonary endothelial cells and early metastatic colonization." (PMID 27564266, 2016). "The relevance of SPARC in the hallmarks of bladder cancer was determined using a carcinogen-induced model providing a tobacco metabolite and chemical carcinogen N-nitrosobutyl(4-hydroxybutyl)amine (BBN) to SP−/− and SP+/+ mice for ∼ 40 weeks." (PMID 27564266, 2016). "Other laboratories performing unbiased secretome analyses have shown that SPARC also mediates cooperation between tumor cell subpopulations with different invasive potentials in ovarian and bladder cancer models." (PMID 25331979, 2014).
bladder cancer (continued). "In bladder cancer, there again was a connection between high SPARC and poor prognosis but additionally, gene expression of SPARC correlated with matrix metalloproteinase-2 (MMP-2) expression." (PMID 22016635, 2011). "BSA modification on the surface of E. coli enhances its ability to adhere and target cancer cells, and we speculate that these characteristics are related to the expression of SPARC in different bladder cancer cell lines." (PMID 37062822, 2023). "The multi-faceted contextual roles of SPARC were discussed in detail in a previous review, and the overall hypothesis was that SPARC exhibited differential expression and functions in the bladder cancer microenvironment." (PMID 33388091, 2021). "Strikingly, SPARC emerged as the top gene (r ≥ 0.9) correlating with CAFs across various cancer types, while its expression was commonly upregulated across different tumors, including cancer of bladder, breast, bile ducts, colon, esophagus, brain, head and neck, liver, and stomach." (PMID 36604669, 2023). "Thus, for bladder cancer patients with high SPARC expression, on the basis of BSA modification of live bacteria, combination with other therapeutics may provide an effective therapeutic strategy." (PMID 37062822, 2023). "Moreover, we found that BSA-modified E. coli had enhanced adhesion and tumor targeting ability, which may be related to the expression of the BSA-binding protein SPARC in bladder cancer cells." (PMID 37062822, 2023). "We found a significant correlation of the increased adhesion of E. coli to bladder cancer cells and the BSA modification, however, the correlation of adhesion ability of E. coli was stronger to the level of SPARC expression in the bladder cancer cells." (PMID 37062822, 2023). "In human bladder cancer tissue microarrays (TMA) that comprised 192 patients’, SPARC protein expression significantly decreased in MI compared to NMI disease." (PMID 27564266, 2016). "SPARC expression was found in stromal cells but not in cancer cells in Sparc+/+ mice with bladder cancer which had lung metastases." (PMID 34209679, 2021). "Enhanced SPARC expression in the tumor-associated stroma correlates with a poor prognosis for patients with non-small cell lung cancers (NSCLC) and pancreatic adenocarcinomas, but not for those with bladder cancers." (PMID 31067787, 2019). "Interestingly, the expression of SPARC protein and transcript were significantly downregulated in tumorigenic bladder cancer cell line T24T compared to its non-tumorigenic isogenic line T24." (PMID 27564266, 2016). "In addition, TCGA data revealed the enrichment of signaling pathways that were inhibited by SPARC in ovarian cancer as phosphatidylinositol-3-OH kinase/AKT/mTOR pathway and the RTK/MAPK pathway suggesting potential inhibitory effect in bladder cancer milieu." (PMID 27564266, 2016).
cervical carcinoma (15 papers, 2009 to 2025). A carcinoma arising from either the exocervical squamous epithelium or the endocervical glandular epithelium. "The treatment of cervical cancer cell lines with demethylating agents, coupled to expression microarrays, has identified the genes encoding SPARC and TFPI2 as highly methylated in invasive cervical cancer." (PMID 22815913, 2012). "Moreover, in patients with cervical carcinoma or ampullary cancer, such overexpression is associated with a poor prognosis, and increased serum SPARC levels have been reported in melanoma patients as well." (PMID 34827687, 2021). "Some studies have also shown that cervical cancer cells exhibited significant expression of secreted protein acidic and rich in cysteine (SPARC) in both the cytoplasm and extracellular matrix." (PMID 38914827, 2024). "Six interesting core DEPs (SPARC, HPX, VCAM1, TFRC, ERN1 and APMAP) were confirmed to be potential plasma diagnostic markers for LVSI and LNM in cervical cancer patients." (PMID 37689639, 2023). "MiR-211 is confirmed to inhibit cells proliferation in thyroid cancer 26 and cervical cancer 38 by regulating secreted protein acidic and rich in cysteine (SPARC), which is an extracellular matrix glycoprotein." (PMID 35912006, 2022). "The treatment of HPV-positive cervical cancer cell lines with demethylating agents, coupled to expression microarrays, has allowed the identification of genes encoding for SPARC and TFPI2 as highly methylated in invasive cervical cancer." (PMID 24383054, 2013). "The mechanisms of SPARC in cervical cancer proliferation, apoptosis and invasion were also researched." (PMID 23050783, 2012). "To understand the mechanism of SPARC in cervical cancer cell proliferation, we used flow cytometry to identify the specific phases of the cell cycle." (PMID 23050783, 2012). "In the function assays, we decreased the expressions of SPARC in high invasive subclones by lentivirus-mediated RNA interference to determine the effects of SPARC on cervical cancer cell proliferation, apoptosis, invasion and metastasis." (PMID 23050783, 2012). "To investigate the role of SPARC in cervical cancer, we constructed lentivirus vector with SPARC shRNA and infected high invasive subclones HeLa-1 and SiHa-1." (PMID 23050783, 2012). "In functional assays, effects of SPARC knockdown on the biological behaviors of cervical cancer cells were investigated." (PMID 23050783, 2012). "Knockdown of SPARC significantly suppresses cervical cancer cell proliferation, induces cell apoptosis and inhibits cell invasion and metastasis." (PMID 23050783, 2012). "Therefore, we believe that these five protein molecules (including SPARC) have the potential to be plasma biomarkers in cervical cancer patients." (PMID 37689639, 2023). "The serum level of SPARC was higher in cervical cancer patients than in healthy controls and CIN patients, and high expression of SPARC was correlated with the LNM of cervical carcinomas, which is consistent with the results of our DIA proteome sequencing study." (PMID 37689639, 2023). "Besides, it is also reported that miR-211 can suppress cells invasion by regulating SPARC in thyroid cancer 26 and cervical cancer." (PMID 35912006, 2022). "However, there are still emerging studies highlighting the role of SPARC in cancer cells proliferation regulation, such as oral squamous cell carcinoma 94, liver cancer 95, and cervical cancer." (PMID 35912006, 2022). "SPARC as a promoter improves cervical cancer cell growth and metastasis." (PMID 23050783, 2012). "SPARC is related to the invasive phenotype of cervical cancer cells." (PMID 23050783, 2012). "However, till now few researches have been done about the functions of SPARC in human cervical cancer cell growth and metastasis." (PMID 23050783, 2012). "Knockdown of SPARC inhibited cervical cancer cells invasion and migration." (PMID 23050783, 2012).
cervical carcinoma (continued). "However, few studies have been done to assess the functions of SPARC in cervical cancer cell growth and metastasis." (PMID 23050783, 2012). "However, no information has been available to date regarding the function of SPARC in cervical cancer cell growth and metastasis." (PMID 23050783, 2012). "It was reported that MT1G, NMES1, RRAD, SFRP1, SPARC and TFPI2 were more often methylated in invasive cervical cancer samples than in normal ones, suggesting that these 6 genes may be potential tumor suppressor candidate for cervical cancer." (PMID 26329329, 2015). "Recently, SPARC has been found over-expressed in a variety of cancers and considered a potential target for cancer therapy, but the function of SPARC in cervical cancer cell growth and metastasis is not fully understood." (PMID 23050783, 2012).
sarcopenia (15 papers, 2014 to 2025). Progressive decline in muscle mass due to aging which results in decreased functional capacity of muscles. "Thus, SPARC decline would be implicated within both sarcopenia as well as ageing process that impacts muscles as well." (PMID 35741776, 2022). "In contrast, it was hypothesized that patients with sarcopenia have lower SPARC levels, which then may have an association with shorter RFS." (PMID 32512862, 2020). "In contrast, patients with sarcopenia were hypothesized to have lower SPARC levels, which may thus have an association with shorter RFS." (PMID 32512862, 2020). "Such Sparc KO-induced phenotype is important to understand the roles of SPARC in sarcopenia and glucose metabolism and to understand the link between ECM remodeling and mitochondrial function." (PMID 36810547, 2023). "In order to further clarify the in vivo roles of SPARC and their similarities with ET, the impacts of Sparc knock-out (KO) in relation to sarcopenia and age-related metabolic disorders in young and old mice have also been investigated." (PMID 36810547, 2023). "On univariate analysis, hazard ratios (HRs) for death were significant for low SPARC levels and sarcopenia." (PMID 32512862, 2020). "This also suggests that SPARC can serve as a potential biomarker for sarcopenia." (PMID 40171198, 2025). "SPARC’s activation is mediated through the phosphatidylinositol 4,5-bisphosphate 3-kinase (PI3K) signaling pathway linked to Insulin-like Growth Factor 1 (IGF-1), making it vital for the prevention of sarcopenia." (PMID 40076821, 2025). "In addition, during aging, the level of SPARC is decreased and SPARC knockout mice showed the sarcopenia phenotype." (PMID 37577356, 2023). "However, patients with higher SPARC levels had better overall survival (OS) than those with lower levels, which remained significant even after multivariate adjustment including sarcopenia." (PMID 32512862, 2020). "Similarly, serum concentrations of SPARC and MIF were higher in the sarcopenia than the normal group (531.5 ± 40.65 versus 409.4 ± 35.47 pg/mL SPARC, p = 0.047, and 25.10 ± 1.19 versus 20.71 ± 0.89 ng/mL MIF, p = 0.008)." (PMID 29872072, 2018). "Therefore, we also hypothesize that SPARC may optimize or act similarly to exercise in order to attenuate muscle atrophy, which, in turn, prevents sarcopenia and age-related diseases." (PMID 36810547, 2023). "Based on the collective results, IL-6, SPARC, MIF and IGF-1 were selected for analysis as potential biomarkers for sarcopenia." (PMID 29872072, 2018). "HRs for relapse or death were not significant for low SPARC levels or sarcopenia on univariate and multivariate analyses." (PMID 32512862, 2020). "The present post hoc analysis was conducted to examine the relationships among serum SPARC levels, psoas muscle index (PMI) values indicating sarcopenia, serum 25-hydroxyvitamin D (25[OH]D) levels, vitamin D supplementation, and relapse or death in these patients." (PMID 32512862, 2020). "People with sarcopenia have higher circulating SPARC levels than those without." (PMID 40171198, 2025). "However, on multivariate analysis, HRs for death as the outcome were significant only for low SPARC levels, not sarcopenia." (PMID 32512862, 2020). "Among the candidates investigated, serum levels of IL-6, SPARC, MIF and IGF-1 were significantly different between normal and sarcopenia groups, but not the other biomarkers (data not shown)." (PMID 29872072, 2018).
type 2 diabetes (14 papers, 2004 to 2025). "Elevated plasma SPARC levels have been detected in individuals with type 2 diabetes mellitus (T2DM)." (PMID 40243151, 2025). "Fibrosis is a clinical feature of hypertension, and both human and animal models support a relationship between SPARC and type 2 diabetes pathogenesis." (PMID 31891604, 2019). "The strength of this study is the identification of a potential novel role for SPARC in the regulation of insulin secretion relevant for the onset of Type 2 diabetes." (PMID 23840838, 2013). "This is concordant with our own observations that SPARC expression is reduced in the islets of patients with type 2 diabetes." (PMID 23840838, 2013). "The SPARC gene is expressed at detectable levels in primary human islets and was found to be lower in the islets of patients with type 2 diabetes, despite a higher BMI in these subjects." (PMID 23840838, 2013). "In the future, it will be interesting to learn whether SPARC can improve insulin secretion in patients with type 2 diabetes through RGS4 pathway." (PMID 33067534, 2020). "However, the serum concentration of SPARC had been detected by a sandwich ELISA method in the type II diabetes mellitus patients." (PMID 15558074, 2004). "Our results do not suggest an increase of SPARC expression in islets of subjects with Type 2 diabetes as may have been expected from its antiproliferative and profibrotic action in adipose tissue." (PMID 23840838, 2013).
endometrial cancer (13 papers, 2008 to 2025). Primary or metastatic malignant neoplasm involving the endometrium (mucous membrane that lines the endometrial cavity). "One study demonstrated that fibronectin secreted by SPARC-expressing endometrial cancer cells activates stromal fibroblasts and enhances EMT, thereby facilitating cancer cell migration and metastasis." (PMID 40805172, 2025). "The in vitro study indicated that overexpression of SPARC in endometrial cancer cells and fibronectin 1 jointly activate fibroblasts, promoting cancer progression and invasion." (PMID 36982551, 2023). "In endometrial cancer (EC), low SPARC expression is related to aggressive EC phenotype and poor prognosis." (PMID 35042833, 2022). "Recent studies showed that SPARC favored the migration and invasion of endometrial carcinoma cells in vitro and in vivo." (PMID 36452484, 2022). "SPARC-expressing endometrial cancer cells activated fibroblasts only in the presence of FN1, which was abundantly secreted from the cancer cells." (PMID 33579227, 2021). "Our data indicated that SPARC activated fibroblasts only in the presence of fibronectin, which was abundantly secreted from SPARC-expressing endometrial cancer cells." (PMID 33579227, 2021). "In our previous study, we found that SPARC was exclusively expressed in endometrial cancer (EC) stem-like cells." (PMID 33579227, 2021). "We investigated the effects of SPARC expression in endometrial cancer cells on the surrounding stromal fibroblasts using in vitro co-culture system." (PMID 33579227, 2021). "SPARC is also overexpressed in endometrial cancer stem-like cells." (PMID 30061686, 2018). "In a model of endometrial cancer, it was demonstrated that SPARC activates fibroblasts in the presence of FN1, which itself was secreted by SPARC-expressing endometrial cancer cells, leading to enhanced mobility and invasion." (PMID 41488007, 2025).